Y_RNA (Y RNA )
Gene: Miscellaneous RNA gene on chromosome 4 (140,779,039 to 140,779,141, reverse strand). Ensembl gene ENSG00000222613.
Homologues: Orthologues: chimpanzee Y_RNA (98% identical), macaque Y_RNA (91% identical). Paralogues in human: Y_RNA (76% identical), RNY1 (74% identical), Y_RNA (74% identical), RNY1P11 (73% identical), RNY1P7 (73% identical), Y_RNA (73% identical), Y_RNA (72% identical), Y_RNA (71% identical), Y_RNA (70% identical), Y_RNA (69% identical), RNY1P8 (68% identical), Y_RNA (68% identical), and 88 more.